IQGAP1 (IQ motif containing GTPase activating protein 1)
Diseases named in the same sentence as IQGAP1 in open-access papers (continued):
Sharing a sentence is not in itself a finding about the gene and the disease.
tumor (continued). "In addition, a significantly higher expression of IQGAP1 and β-catenin also usually exists in human HCC tissues, especially their overexpression is clinicopathologically associated with tumor malignancy." (PMID 26252773, 2015). "IQGAP2 displays anti-tumor activity, despite its structural similarity to IQGAP1." (PMID 24849319, 2014). "Indeed, recent research indicate also that IQGAP1 and IQGAP2 fulfill distinct functions in tumorigenesis, whereas IQGAP1 acts as an oncogene IQGAP2 seems to act as a tumor suppressor." (PMID 24281338, 2012). "Our findings suggest a functional link between PALB2 protein and alterations in IQGAP1 expression and subcellular localization which may contribute to tumor progression through the deregulation of cellular proliferation, migration, and cytoskeletal organization." (PMID 40868059, 2025). "IQGAP1 staining in case P-T2 reaches a medium intensity level in cytosol and high intensity in the periphery and in the plasma membrane; β-tubulin immunofluorescence has a high intensity level in the cytosol of tumor cells and to a lesser extent in stroma cells." (PMID 40868059, 2025). "Samples from the PALB2-mutated case P-T2 showed staining for IQGAP1 at medium intensity in cytosol, becoming high-intensity in the periphery and in the plasma membrane; CK7-specific staining was at saturation level in the cytosol of tumor cells, leaving a noticeable intercell space." (PMID 40868059, 2025). "By reducing TGFβR2 protein levels, IQGAP1 inhibits TGF-β1-driven differentiation of pericytes into tumor-associated myofibroblasts, suggesting that the inhibitory TGFβR2:IQGAP1 interaction may constrain tumor growth." (PMID 37071417, 2023). "Furthermore, IQGAP1 enhanced extracellular matrix (ECM) degradation by binding to the exocyst subunits via RGCT domain to prime tumor cell metastasis and invasion, while the elimination of the exocyst binding site abrogated the enhancement of IQGAP1-induced ECM degradation." (PMID 35785216, 2022). "However, the role of IQGAP1 in tumor development and metastasis remains unclarified." (PMID 36276098, 2022). "Therefore, IQGAP1 plays an important role in cancer development, and anti-tumor therapy targeting IQGAP1 interacting proteins or related pathways may be beneficial for tumor therapy." (PMID 36275458, 2022). "Therefore, elevated IQGAP1 in tumor tissues may contribute to poorer patient prognosis by promoting tumor cell shedding, metastasis, and invasion." (PMID 36320006, 2022). "Further investigation into how IQGAP1 promotes disease progression may shed additional insights into papillomavirus-induced carcinogenesis and provide new drug targets for treating HPV-associated neoplastic disease." (PMID 34068608, 2021). "Interestingly, IQGAP1 seems to have a different role when expressed in the tumor microenvironment." (PMID 34439095, 2021). "However, the two tumor types shared aggregated IQGAP1 in the cytosol." (PMID 32655836, 2020). "Thus, in addition to the marked role for IQGAP1 in extravasation that we have identified, this versatile scaffold protein may have further roles in directing tumor growth, regulating EMT and coordinating other known metastasis promoters." (PMID 32051509, 2020). "However, the relationship between IQGAP1 and Dvl in tumor tissues is unclear." (PMID 25436461, 2014). "By forming a complex with ARF1, IQGAP1 activates the ERK signaling pathway, which enhances tumor cell invasiveness and confers resistance to BRAFV600E inhibitors, such as vemurafenib." (PMID 41035668, 2025). "IQGAP1 mediates the activation of multiple signaling pathways, including EGFR and CXCR4, which are crucial for tumor cell behavior." (PMID 41035668, 2025). "Specifically, an elevation in the expression levels of PRN1, OXSM, SLC3A2, and CD2AP were observed in tumor tissues, while the expression levels of DSTN, FLNA, TLN1, IQGAP1, MYL6, NCKAP1, and NDUFS1 declined in tumor tissues." (PMID 39995998, 2025).
tumor (continued). "Their research shows that IQGAP1 affects AS of components in the electron transport chain (ETC), enhancing oxidative metabolism in GC cells, thus facilitating tumor proliferation and invasiveness." (PMID 39179991, 2024). "Results showed that ACTB, DSTN, FLNA, IQGAP1, MYL6, and TLN1 were overexpressed in normal tissues, while CD2AP and INF2 were overexpressed in tumor tissues." (PMID 37325625, 2023). "In esophageal tumors, IQGAP1 overexpression enhances VEGF expression and VEGFR2 activation, which stimulates angiogenesis to favor tumor progression." (PMID 37071417, 2023). "IQGAP1 also binds constitutively to LGR5, another LGR that potentiates Wnt/β-catenin signaling with both oncogenic and tumor suppressor roles in colorectal carcinoma." (PMID 37071417, 2023). "IQGAP1 and IQGAP3 are overexpressed in a wide array of neoplasms and are considered to be oncogenes." (PMID 37071417, 2023). "Further, in the final stage of the experiment, mice were sacrificed and the protein expression level of IQGAP1 and FOXM1 in the excised tumor samples was analyzed using western blotting." (PMID 37202772, 2023). "IQGAP1 and 3 are upregulated and are considered oncogenes in HCC, while IQGAP2 is downregulated and functions as a tumor suppressor." (PMID 35785216, 2022). "WW domain of IQGAP1, through a polyproline motif, binds to classical MAP kinases (MAPK) and activates downstream signaling pathways and advances tumor development, growth, and invasion." (PMID 35785216, 2022). "IQGAP1 is considered an oncogene in HCC as its mRNA and protein levels are elevated in human HCC tissues compared to para-tumor and normal liver tissues." (PMID 35785216, 2022). "The study showed that in colon and lung cancer liver metastases, IQGAP1 binds to TβRII and suppresses TβRII-mediated signaling to prevent HSC differentiation in the tumor microenvironment and constrains metastatic tumor growth." (PMID 35785216, 2022). "In contrast, IQGAP2 is thought to play the opposite role of IQGAP1 in HCC, displaying functions resembling a tumor suppressor." (PMID 36320006, 2022). "While IQGAP2 shares an overall 62% homology with IQGAP1 with even higher levels of homology between their respective structural motifs except the WW domain, IQGAP2 surprisingly possesses tumor suppressive activities." (PMID 33498739, 2021). "IQGAP1 expression was positively correlated with the expressions of HBsAg and AFP, tumour size and number, and BCLC stage." (PMID 32632148, 2020). "However, the role of IQGAP1 in tumor progression and metastasis remains unclear." (PMID 32051509, 2020). "We compared metastatic burden in the lungs and liver between the wild-type and IQGAP1 knockout cell lines and observed an overall reduction in metastasis to both organs following the loss of IQGAP1, implying that IQGAP1 has an effect on metastasis independent of primary tumor growth." (PMID 32051509, 2020). "Based on the clinicopathological information, we found that a higher level of IQGAP1 expression was positively correlated with HBsAg and AFP level, tumour size and number and BCLC stage." (PMID 32632148, 2020). "We observed that the knockdown of IQGAP1 in the two cell lines SW1990 and CFPAC-1 not only inhibited cell proliferation in vitro but also suppressed tumor growth and metastasis in vivo." (PMID 31101875, 2019). "To ascertain the role of IQGAP1 in antitumor immunity, we employed the RMA-RMA/S tumor clearance model as an in vivo evaluation of NK cell function." (PMID 29892299, 2018). "Targeting IQGAP1 reduces ERK1/2 pathway activity in neoplastic cells while preserving normal ERK1/2 MAPK function in physiologically normal cells, demonstrating a tumor-specific efficacy." (PMID 28445541, 2017). "Tissue-penetrating peptides that block IQGAP1 and ERK interactions decreased MAPK-driven tumor growth." (PMID 28463969, 2017).
tumor (continued). "IQGAP1 immunoreactivity in GBM tissue sections exhibited a variable pattern of expression, depending on the origin of tumor (patient case), area of tumor and even in specific astrocytes within the same tumor." (PMID 28098764, 2017). "Knocking down IQGAP1 impairs tumor cell growth, migration and invasion and the reversal of the EMT program, indicating that IQGAP1 expression is important for the induction of EMT." (PMID 26934121, 2016). "IQGAP1 is often overexpressed in many solid tumors (other than EC) and is a key promoter of the EMT program, tumor cell migration, invasion, proliferation and angiogenesis." (PMID 26934121, 2016). "Here we have shown that IQGAP1 induces EMT and enhances EC invasion, and also identified miR-124 as an epigenetically silenced tumor suppressor that inhibits the EC cell migration, invasion and proliferation, by down-regulating oncogene IQGAP1 expression." (PMID 26934121, 2016). "MiR-124, a novel tumor suppressor miRNA that is epigenetically silenced in EC, can reverse EMT and the invasive properties, by attenuating the expression of the IQGAP1 oncogene." (PMID 26934121, 2016). "And a significantly higher expression of IQGAP1 and β-catenin also usually exists in human HCC tissues; especially their overexpression is clinically correlated with tumor malignancy or differentiation degree." (PMID 26252773, 2015). "IQGAP1 has been shown to be enriched at invadopodia in MDA-MB-231 cells, structures that form at contact sites between invasive tumor cells and the extracellular matrix." (PMID 23405264, 2013). "In the present study, our aim was to examine IQGAP1 and IQGAP2 expression in human HCC, their sensitivity and specificity as biomarkers of this type of tumor, and the methylation profile of the Iqgap2 promoter." (PMID 20977743, 2010). "Viewed collectively, these data strongly suggest that IQGAP1 and IQGAP2 contribute to the pathogenesis of HCC, and that these proteins are highly sensitive and specific biomarkers of this type of tumor." (PMID 20977743, 2010). "The absence of tumor cells with predominant IQGAP1 expression over CK7 in the mutant background further underscores a possible deregulation of IQGAP1 compartmentalization and function upon PALB2 truncation." (PMID 40868059, 2025). "In conclusion, IQGAP1 mediates tumor drug resistance through multiple mechanisms, including the suppression of ferroptosis via YAP activation, ROS-induced Src/FAK signaling, sustained MAPK activation, and ARF1-IQGAP1 complex-driven ERK activation." (PMID 41035668, 2025). "The expression of IQGAP1 is positively correlated with CDC42, Ih promotes tumor malignancy." (PMID 41035668, 2025). "Similarly, downregulating IQGAP1 in MCF7 cells using siRNAs diminishes cell migration, proliferation and prevents tumor formation in xenograft mice." (PMID 37892237, 2023). "Likewise, interruption of IQGAP1-kinase- connections by ectopic expression of WW peptide in mice selectively suppressed Ras-MAPK -mediated oncogenesis and tumor invasion." (PMID 35785216, 2022). "Moreover, in an experimental liver metastasis model, Iqgap1-/- mice showed higher levels of TGF-β receptor and HSC activation, which promoted metastatic tumor growth." (PMID 35785216, 2022). "Multivariate analysis indicated that multiple tumor numbers, positive IQGAP1, negative IQGAP2, and positive IQGAP3 expressions were independent prognostic factors for RFS." (PMID 36320006, 2022). "In HCC tissues, IQGAP1 expression is positively correlated with tumor size, number, stage, and HBV surface antigen (HBsAg) and alpha-fetoprotein (AFP) expression but inversely correlated with tumor differentiation." (PMID 35785216, 2022). "Both IQGAP1 and IQGAP3 are considered oncogenes in HCC and, thus, can serve as highly sensitive and specific biomarkers for this type of tumor, while IQGAP2 may act as a tumor suppressor." (PMID 36559011, 2022).
tumor (continued). "Targeting IQGAP1 does not impact the primary ER-negative tumor growth but reduces its spontaneous metastasis to both the lung and liver." (PMID 34439095, 2021). "In comparison, among 16 downregulated genes relative to IQGAP1 under-expression, FAM65B (RIPOR2), PI15, and HDAC9 are downregulated in either iCluster 1, iCluster 2, or both in comparison to the matched non-tumor tissues." (PMID 33498739, 2021). "In our previous HPV-negative HNSCC studies, we observed such a phenomenon, i.e., a high dose of 4NQO masked the tumor-suppressing effect resulting from an absence of IQGAP1." (PMID 34068608, 2021). "Phosphorylation of IQGAP1 on Tyr-1510 in some tumors may alter AKT (and perhaps other signaling pathways) to influence tumor growth or progression." (PMID 33087447, 2020). "Using the NK cell-depleted condition as a standard for no tumor clearance, we calculated the percent cytotoxicity of Iqgap1−/− NK cells and found that it was significantly reduced when compared with the IgG (WT) control." (PMID 29892299, 2018). "The significance of such selectivity remains to be determined, however we speculate that IQGAP1 and IQGAP3 may cooperate in regulation of ERK signaling, thereby exerting a synergistic effect on tumor progression." (PMID 24849319, 2014). "IQGAP1 has well documented oncogenic potential and IQGAP2 has putative tumor-suppressive function." (PMID 24849319, 2014). "Expression in U87-MG and U118 cell lines, PA-NAV, PA-GAS and PA-PET initial tumor specimen and in the excised tumor of the case report: we quantified the ICAM1, CRK, CD36, and IQGAP1 mRNA expression in our in vitro models and in the surgical specimen of the case report." (PMID 24252689, 2013). "This study characterized miR-124 and miR-203 as novel tumor-suppressive miRNAs in HCC and may provide an explanation for the observed upregulation of IQGAP1 in human HCC tumors." (PMID 22973521, 2012). "Here, we searched for a binding partner for the WW domain of IQGAP1, motivated by recent findings that a cell-penetrating version of this domain has potent anti-tumor properties with minimal toxicity to non-transformed cells and tissues (see Introduction for further details)." (PMID 37145016, 2023). "Hundreds of studies have clarified and summarized that IQGAP1 is able to interact with and activate different oncogenic pathways, including the MAPK, RAC1/CDC42, Wnt/β-catenin, PI3K, Hippo, and TGF-β pathway, as well as ultimately promoting tumor proliferation, migration, and invasion." (PMID 36831467, 2023). "The up-regulation of IQGAP1 in tumor cells as opposed to healthy cells has also been demonstrated." (PMID 36276098, 2022). "Furthermore, MISP has been reported to interact with and regulate IQ motif containing GTPase activating protein 1 (IQGAP1), a protein that plays a vital role in the progression of PDAC by facilitating epithelial-mesenchymal transition (EMT) and affecting the tumor microenvironment." (PMID 35433491, 2022). "However, despite the complete lack of IQGAP1, there was no reduction in primary tumor growth; in fact, one of the clonal knockout lines had significantly increased primary tumor mass." (PMID 32051509, 2020). "The absence of IQGAP1 and β-tubulin co-immunostaining shows groups of tumor cells undergoing EMT." (PMID 28441737, 2017). "Therefore, antagonists that disrupt the binding of IQGAP1 to RAC1 and/or CDC42 could prevent tumor invasion, proliferation, and migration and could act as specific chemotherapeutic agents." (PMID 27815503, 2016). "Multivariate analysis indicated that multiple tumor numbers, advanced TNM stage, positive IQGAP1, negative IQGAP2, and positive IQGAP3 expressions were independent prognostic factors for OS." (PMID 36320006, 2022). "Univariate analysis showed that larger tumor size, multiple tumor numbers, microvascular invasion, poor tumor differentiation, advanced TNM stage, positive IQGAP1, negative IQGAP2, and positive IQGAP3 expressions were prognostic factors for RFS." (PMID 36320006, 2022).
tumor (continued). "Unlike the oncogene IQGAP1, IQGAP2 is considered to be a tumor suppressor (Smith, Hedman & Sacks, 2015)." (PMID 36275458, 2022). "The homogeneous distribution of IQGAP1 in normal cells shifts to a broad expression pattern, ranging from no expression to high level of expression in the whole CRC tumor cell." (PMID 28441737, 2017). "In tumor lesions, CRC cells exhibited a heterogeneous staining, with clusters of IQGAP1 negative cells mixed with IQGAP1+ cells where the protein was localized in cytoplasm, lateral membrane, nuclear envelope and/or nucleus." (PMID 28441737, 2017). "Interestingly, xenograft tumor lysates from the HC-D group showed higher expression of both IQGAP1 (2.85 ± 0.50, p = 0.003) and caveolin-1 (3.0 ± 0.7, p = 0.011), although cholesterol treatment of PC-3 cells in vitro increased expression of IQGAP1 but not caveolin-1." (PMID 25924234, 2015). "Besides, univariate analysis showed that multiple tumor numbers, microvascular invasion, poor tumor differentiation, advanced TNM stage, positive IQGAP1, negative IQGAP2, and positive IQGAP3 expressions were prognostic factors for OS." (PMID 36320006, 2022). "However, unlike IQGAP1, IQGAP2 serves as a tumor suppressor in the liver." (PMID 34439095, 2021).